CCL11 (C-C motif chemokine ligand 11)
Diseases named in the same sentence as CCL11 in open-access papers (continued):
Sharing a sentence is not in itself a finding about the gene and the disease.
Hypertension (3 papers, 2012 to 2025). The presence of chronic increased pressure in the systemic arterial system. "Above all, therelevance of CCL11 in multiple hypertension processes has been proven.Nevertheless, a clear clarification of the definite association between these twoobjects has yet to be proposed, and the mechanism underlying such a relationshipremains to be revealed." (PMID 40026499, 2025). "Moreover, CCL11 has been selected in developing a clinical andproteomics multiple-marker scoring strategy to diagnose obstructive peripheralarterial disease (PAD), and higher concentrations of CCL11 were notably detectedin patients with severe PAD (history of hypertension)." (PMID 40026499, 2025).
idiopathic retroperitoneal fibrosis (3 papers, 2017 to 2024). "The elevation of the chemokine CCL11 was already associated with damage to various organs, as shown in idiopathic retroperitoneal fibrosis and liver cirrhosis patients." (PMID 29026368, 2017). "Mangieri study also demonstrated higher serum CCL11 levels in patients with idiopathic retroperitoneal fibrosis." (PMID 39444816, 2024).
Insulin resistance (3 papers, 2023 to 2024). Increased resistance towards insulin, that is, diminished effectiveness of insulin in reducing blood glucose levels. "Several studies have shown that elevated levels of CCL2, CCL3 and CCL11 are associated with insulin resistance contributing to the development of T2DM33." (PMID 38092892, 2023). "CCL11 contributes to the development and progression of T2DM by enhancing inflammatory responses and promoting insulin resistance." (PMID 39574905, 2024).
leprosy (3 papers, 2009 to 2025). Leprosy is a chronic infectious disease affecting primarily the skin and peripheral nervous system. "Plasma levels of the chemokines CCL2, CCL3 and CCL11 can be detected in patients with leprosy lesions and remain unchanged after leprosy treatment." (PMID 38381878, 2024). "Recently, greater plasma concentrations of CCL11 have been shown in Brazilian MB leprosy patients, when compared to non infected individuals." (PMID 19473542, 2009).
liver cirrhosis (3 papers, 2017 to 2025). "CCL11 is involved in chronic inflammation, which facilitates the development of liver cirrhosis and fibrosis." (PMID 39338294, 2024).
liver fibrosis (3 papers, 2011 to 2025). "CCL24 has many properties comparable with CCL11, and may be able to promote granuloma formation and hepatic fibrosis via a similar mechanism." (PMID 21666794, 2011). "Expression of the gene regulated on activation, T cell expressed, and secreted (RANTES; Ccl5), which is associated with severe liver fibrosis, was also significantly upregulated in HFHC-fed Dpp4–/– mice, whereas no changes in Mcp-1 (Ccl2) or Eotaxin (Ccl11) gene expression were noted." (PMID 36472923, 2023).
neuromyelitis optica spectrum disorder (3 papers, 2012 to 2022). "Consistent with our results, a few studies have shown that in patients with neuroinflammatory diseases, the serum and liquor samples of CCL11 levels were higher, including in neuromyelitis optica spectrum disorders." (PMID 36291442, 2022). "Adjusted regression coefficients (β) of CCL13, CCL11, and CCL26 levels with relapse times, ARR, and EDSS scores as outcomes in neuromyelitis optica spectrum disorder patients." (PMID 29497397, 2018).
oral squamous cell carcinoma (3 papers, 2014 to 2024). "In oral squamous cell carcinoma with tumor-associated tissue eosinophilia (TATE), the source of CCL11/eotaxin is apparently eosinophils." (PMID 25426119, 2014).
Parkinson disease (3 papers, 2020 to 2025). A progressive degenerative disorder of the central nervous system characterized by loss of dopamine producing neurons in the substantia nigra and the presence of Lewy bodies in the substantia nigra and locus coeruleus. "Inspired by such findings, a startup called Alkahest has initiated a Phase II clinical trial investigating ALK4290, the first non–plasma-derived product targeting CCL11, for treatment of wet age-related macular degeneration (AMD) and Parkinson’s disease." (PMID 33197235, 2020).
periodontitis (3 papers, 2021 to 2023). An acute or chronic inflammatory process that affects the tissues that surround and support the teeth. "Another study identified CCL2, CCL11, years of smoking, and age as periodontitis associated factors." (PMID 36013449, 2022). "Studies in patients with chronic periodontitis and aggressive periodontitis showed reduced blood levels of CCL5 compared to healthy subjects and reduced plasma levels of CCL11 and CXCL9 in patients with chronic periodontitis." (PMID 38139161, 2023). "Indeed, high levels of CCL11, also named Eotaxin-1/C-C motif chemokine 11, CXCL12, also referred to as stromal cell-derived factor-1 (SDF-1) and CCL7, also known as monocyte chemotactic protein-3 (MCP-3) were suggested as biomarkers for periodontitis." (PMID 35048045, 2021).
pulmonary tuberculosis (3 papers, 2012 to 2023). A bacterial infection that affects the lungs and is caused by Mycobacterium tuberculosis. "We found that CCL8, CCL11 and IP-10 did not significantly differ between pulmonary tuberculosis and tuberculous pleurisy patients." (PMID 23028695, 2012).
rectal cancer (3 papers, 2007 to 2023). A primary or metastatic malignant neoplasm that affects the rectum. "On the contrary, levels of CXCL6 and CCL11 showed strong correlations with anastomotic leakage in patients with rectal cancer, further supported by the sensitivity analysis." (PMID 35652588, 2022). "As a hypothetical source of the observed differences in circulating CXCL6 and CCL11 levels between rectal cancer cases and controls, immunohistochemical staining of normal tissues from the resection margin displayed no obvious differences between the two groups." (PMID 35652588, 2022). "In this explorative matched case–control study, patients with rectal cancer with anastomotic leakage had significantly elevated preoperative serum levels of the inflammation-related proteins CXCL6 and CCL11, after correction for multiple comparisons." (PMID 35652588, 2022). "Interestingly, rectal cancer patients presenting with AL might have an upregulated inflammatory response preoperatively with increased serum levels of C-X-C motif chemokine 6 (CXCL6) and C-C motif chemokine 11 (CCL11)." (PMID 36975449, 2023).
renal cell carcinoma (3 papers, 2016 to 2024). "In renal cell carcinoma, CCR3 facilitates tumor proliferation and metastasis through the CCL11/CCR3 axis." (PMID 38511143, 2024).
viral infection (3 papers, 2017 to 2023). "Several chemokines were also involved in response to viral infection (CCL4, CCL11, CXCL10), bacterial infection (CCL2, CCL3, CXCL10), as well as to toxic substances insults (CCL3, CCL4)." (PMID 32295518, 2020). "TNFAIP3, ULBP1 and TIAM1 were consistently down-regulated by viral infection, while CCL8, CCL11, CXCL11, NCF2, CSF3 and PRKCB were significantly up-regulated after infection." (PMID 28938587, 2017).
anaplastic large cell lymphoma (2 papers, 2024 to 2025). Anaplastic large cell lymphoma (ALCL) is a rare and aggressive peripheral T-cell non-Hodgkin lymphoma, belonging to the group of CD30-positive lymphoproliferative disorders, which affects lymph nodes and extranodal sites. "The interaction between CCL11 and CCR3 enhances the survival of anaplastic large cell lymphoma cells via ERK1/2 activation." (PMID 38305920, 2024). "Moreover, CCL11 may act in an autocrine manner in anaplastic large cell lymphoma (ALCL) to promote tumor growth." (PMID 38305920, 2024).
anxiety disorder (2 papers, 2016 to 2019). A category of psychiatric disorders which are characterized by anxious feelings or fear often accompanied by physical symptoms associated with anxiety. "Additionally, AUD patients with comorbid depressive and/or anxiety disorders have been reported to have alterations in the plasma levels of the chemokine eotaxin-1 (CCL11)." (PMID 30870525, 2019). "Regarding the association between anxiety disorders and CCL11 concentrations, we found no studies in addicted subjects and only a study in anxious subjects with obsessive–compulsive disorder has examined this chemokine in the plasma but no changes were reported." (PMID 28149283, 2016).
breast invasive carcinoma (2 papers, 2019 to 2024). "The expression of CCL11 in invasive breast cancer (BRCA) was analyzed using TCGA database." (PMID 38305920, 2024).
breast tumors (2 papers, 2020 to 2025). "Hypoxia also increases TAM recruitment to breast tumors by increasing CCL11/eotaxin-1 expression." (PMID 32781743, 2020).
Cerebral ischemia (2 papers, 2019 to 2022). Restriction of arterial blood supply to the brain associated with insufficient oxygenation to support the metabolic requirements of the tissue. "It has been demonstrated in a neonatal mouse model of cerebral ischemia, CCL11 levels are also upregulated after cerebral ischemia, which results in promoting migration of NSPCs in these mice." (PMID 35281473, 2022). "Recent evidence suggests that CCL11 levels are also upregulated after cerebral ischemia in neonatal mice, which results in promoting migration of NPCs in these mice." (PMID 31888056, 2019). "Hence, the present work for the first time analyzed the impact of ectopic CCL11 in a model of cerebral ischemia in both adolescent and adult mice." (PMID 31888056, 2019). "Hence, the cytokine CCL11, known to also pass the intact blood-brain barrier (BBB), has recently been recognized as an interesting target under conditions of CNS diseases not limited to cerebral ischemia alone." (PMID 31888056, 2019). "As cerebral ischemia involves a plethora of signaling pathways, not only limited to inflammation but also including cell survival pathways, we next evaluated whether or not CCL11 affects autophagy or apoptotic pathways." (PMID 31888056, 2019).
cerebral malaria (2 papers, 2017 to 2018). A sequestration of Plasmodium falciparum in the brain, which can cause coma and/or seizures. "In the mice model of experimental cerebral malaria, CCL11 was elevated in the hippocampus and frontal cortex." (PMID 28173860, 2017).
chronic bronchitis (2 papers, 2007 to 2009). A type of chronic obstructive pulmonary disease characterized by chronic inflammation in the bronchial tree that results in edema, mucus production, obstruction, and reduced airflow to and from the lung alveoli. "CCL11/Eotaxin is involved in eosinophil recruitment, and CCL11/eotaxin concentrations are increased in the sputum of patients with exacerbations of chronic bronchitis." (PMID 17868461, 2007).
cocaine use disorder (2 papers, 2016 to 2020). A substance-related disorder that involves the recurring use of cocaine despite negative consequences. "For instance, CCL11 has been recently identified as a chemokine linking cocaine use disorders with major depression." (PMID 31974503, 2020).
delirium (2 papers, 2022 to 2025). A disorder characterized by confusion; inattentiveness; disorientation; illusions; hallucinations; agitation; and in some instances autonomic nervous system overactivity. "We identified several soluble factors and immune cell types linked to delirium, including IL-1α, IL-22, IL-21, CCL11, CXCL1, CXCL13, and VEGF-A, as well as exhausted B cells and activated T cells." (PMID 41219650, 2025). "While CXCL1 has been previously associated with delirium, associations with CCL11, CXCL13, and VEGF-A are novel findings, likely due to limited prior investigations of these markers in delirium." (PMID 41219650, 2025). "Notably, CCL11, CXCL1, CXCL13, and VEGF-A remained significantly associated with delirium after adjusting for confounding factors." (PMID 41219650, 2025). "Overall, delirium was correlated with several cytokines (decreased IL-22, IL-21, IL-1α), chemokines (increased CXCL1, CCL11, CXCL13), and growth factors (increased HGF, and a tendency towards increased VEGF-A)." (PMID 41219650, 2025). "However, there are no data whether delirium is associated with M1 macrophage, Th1, Th2, Th17, Treg or CIRS cytokine profiles, and whether a neurotoxic cytokine profile including M1, Th1, Th17 and neurotoxic chemokines, such as CCL11, CCL2, CCL3, CCL5, and CXCL10) is associated with delirium." (PMID 35641947, 2022).
endotoxemia (2 papers, 2012 to 2016). "However, it is worth mentioning that CCL11/eotaxin-1, besides its role in attracting eosinophils, can exert a specific regulatory function of neutrophil recruitment in vivo as has been shown in a mouse model of endotoxemia via probable down-regulation of CXC chemokine CXCL8/IL-8." (PMID 22529962, 2012).
fibrosarcoma (2 papers, 2022 to 2025). A malignant mesenchymal fibroblastic neoplasm affecting the soft tissue and bone. "This is supported by the findings from a study that included three groups of mice deficient in C-C motif chemokine ligand 11 (CCL11), both CCL11 and IL-5, and eosinophils, respectively; all the three groups of mice exhibited increased tumor growth in chemically-induced fibrosarcoma." (PMID 35844571, 2022).
Granuloma (2 papers, 2020 to 2022). A compact, organized collection of mature mononuclear phagocytes, which may be but is not necessarily accompanied by accessory features such as necrosis. "Studies in vitro showed that myofibroblasts release CCL11 and IL-5, crucial molecules for the recruitment and accumulation of eosinophils in granulomas." (PMID 36296298, 2022).
head and neck cancer (2 papers, 2022 to 2024). A primary or metastatic malignant neoplasm affecting the head and neck. "CCL11 administration promoted the migration and invasion of head and neck cancer (HNC) cells with enhanced cancer stem cell-like properties and induction of epithelial-to-mesenchymal transition." (PMID 35804913, 2022). "Expression of CCL11 and CCR3 promotes tumor aggressiveness in head and neck cancer." (PMID 38305920, 2024).
injury (2 papers, 2019 to 2025). Damage inflicted on the body as the direct or indirect result of an external force, with or without disruption of structural continuity. "CCL11 promotes the migration and proliferation of neural progenitor cells and plays a crucial role in neuroregeneration after neonatal hypoxic–ischemic brain injury." (PMID 40563933, 2025).
liver cancer (2 papers, 2019 to 2024). An epithelial or non-epithelial malignant neoplasm that arises from the liver. "CCL11 is believed to function by activating the CCR3 receptor, which enhances VEGF expression in liver cancer cells and promotes tumor angiogenesis." (PMID 38305920, 2024).
lung diseases (2 papers, 2022 to 2023). "Like Th2 cytokines, eotaxin (CCL11) is associated with eosinophil migration and activation in lung diseases." (PMID 36560488, 2022). "Since senescent fibroblasts are involved in deleterious alterations in lung diseases, we sought to evaluate the impact of CCL11 on cellular senescence in the MRC5 human-derived fibroblast cell line." (PMID 37860000, 2023). "Collectively, our findings provide evidence that CCL11 is capable of inducing cellular senescence in human lung-derived fibroblasts, which may contribute to pathological extracellular matrix alterations in lung diseases." (PMID 37860000, 2023).
neuropathic pain (2 papers, 2019 to 2021). Chronic pain caused by damage to nerve fibers. "Interestingly, our results show substantial increases in the levels of the CCL7 and CCL11 mRNAs in the spinal cord and/or DRG in the early and late stages of neuropathic pain." (PMID 34795678, 2021).
pneumonia (2 papers, 2023 to 2024). An acute, acute and chronic, or chronic inflammation focally or diffusely affecting the lung parenchyma, caused by an infection in one or both of the lungs (by bacteria, viruses, fungi, or mycoplasma.). "Specifically, FOXM1 can affect inflammation in pneumonia through NF-κB and the JAK/STAT signaling pathway and FOXM1 deficiency reduces the expressions of CCL11, CCL24 and chemokine receptors CCR2 and CX3CR1 to further affect inflammation." (PMID 36964598, 2023). "Although the concentrations of IL-13, IL-17A, MIP-1α/CCL3, PAI1, sCD14, IL-1β, CCL11/eotaxin, VEGF/VPF, and RANTES/CCL5 did not exhibit significant differences between the HIV and pneumonia and HIV-only groups, several reasons could explain this lack of disparity." (PMID 38251391, 2024).
prostate (2 papers, 2014 to 2018). "Some anti-angiogenesis related genes were essentially down-regulated in PC3 cells, i.e. MMP2, TNF-alpha, CCL11 and the potent pro-angiogenic factor IGF1 (9 fold down-regulation) which is deeply involved in prostate carcinogenesis and identified as autocrine proliferation stimulus for hPCa cells." (PMID 24681516, 2014).
sarcoma (2 papers, 2023 to 2025). A usually aggressive malignant neoplasm of the soft tissue or bone. "CCL11-overexpressing MS-K sarcoma cell clones (MS-K-CCL11) demonstrated higher eosinophil recruitment and BM eosinophil differentiation." (PMID 37587450, 2023).
synovitis (2 papers, 2021 to 2025). Inflammation of a synovial membrane. "Whereas CCL2 and CCL3 returned to baseline levels within 24 h, CCL5 and CCL11 remained elevated from baseline for 72 h in the synovitis model." (PMID 33980227, 2021). "CCL11 was increased from baseline at 6–72 h post-synovitis and at 6 and 12 h post-lavage (synovitis CCL11 baseline: 3288 ± 2521 pg/mL; synovitis CCL11 peak: 16,225 ± 2520 pg/mL, p = 0.0001; lavage CCL11 baseline: 1951 ± 2521 pg/mL; lavage CCL11 peak: 9883 ± 2520 pg/mL, p = 0.002)." (PMID 33980227, 2021).
abdominal aortic aneurysm (1 paper, 2024). Enlargement and ballooning of the vessel that supplies arterial blood to the abdomen, pelvis and legs. "CCL11 has an increased expression in cerebral aneurysms and abdominal aortic aneurysms (AAA), which indicates the potential usage as a biomarker in AAA and a possible therapeutic target for the prevention of aneurysm formation and rupture." (PMID 38906863, 2024).
acute leukemia (1 paper, 2017). A clonal (malignant) hematopoietic disorder with an acute onset, affecting the bone marrow and the peripheral blood. "Serum samples from CRMO patients contained higher concentrations of CCL4/MIP-1β, CCL5/RANTES, CCL11/eotaxin, S100A8, and lower concentrations of IL-18, sIL-2R, and osteoprotegerin when compared to samples from patients with acute leukemia." (PMID 29250517, 2017).
airway allergy (1 paper, 2017). "Indeed, the coexpression of Ccl11 and Ccl24,45 or IL-5 and Ccl24,46 correlates with persistent airway eosinophilia in mice with severe airway allergy." (PMID 27484038, 2017).
Alcohol Use Disorders (1 paper, 2016). "Therefore, alcohol abuse and/or dependence could induce changes in CCL11 concentrations interfering in the expected effects of age and emphasizing sex differences." (PMID 28149283, 2016).
anemia (1 paper, 2020). A reduction in the number of red blood cells, the amount of hemoglobin, and/or the volume of packed red blood cells. "Our analysis supports this finding, as higher CCL11 plasma concentration at recruitment was associated with higher Hb levels at delivery, and we had established previously that clinical Pv infection is associated with maternal anemia." (PMID 32365058, 2020).
arteriosclerosis (1 paper, 2020). A vascular disorder characterized by thickening and hardening of the walls of the arteries. "CCL11 is a chemokine, acting as a chemoattractant for eosinophils and plays a role in arteriosclerosis, inflammation and neurogenesis." (PMID 32489700, 2020).
atopic asthma (1 paper, 2023). An asthma that is characterized by symptoms that are triggered by an allergic reaction caused by inhaled allergens such as dust mite allergen, pet dander, pollen and mold. "Furthermore, our data reveal an increased expression of multiple aging markers within AECs from atopic asthma patients, accompanied by heightened CCL11 secretion." (PMID 37860000, 2023).